CD34 (CD34 molecule)
Diseases named in the same sentence as CD34 in open-access papers (continued):
Sharing a sentence is not in itself a finding about the gene and the disease.
neurofibroma (continued). "Although immunohistochemistry does not significantly aid in distinguishing ANNUBP from neurofibromas, varying degrees of loss in S-100/SOX-10 expression and the CD34+ fibroblast network may correlate with tumor malignancy." (PMID 40308487, 2025). "In fact, the only reliable immunomarker for this neoplasm, to date, remains to be CD34, which, although highly sensitive, is not specific, as some cases of dermatofibromas and neurofibromas may be, at least focally, positive." (PMID 33445443, 2021). "CD34 is not specific for SFTs, as weak and usually patchy staining may be visualized in meningiomas, neurofibromas, and hemangiopericytomas." (PMID 26155787, 2015). "However, CD34 is not specific for SFTs, as weak and usually patchy staining may be visualized in meningiomas, neurofibromas, and hemangiopericytomas." (PMID 30508695, 2019). "A crucial differential diagnosis is the GIST, which can also express S100 and CD34 but will typically be positive for CD117 and almost always positive for DOG1, unlike neurofibromas." (PMID 39070511, 2024). "Immunohistochemistry is positive for CD34 and CD99, more variably for EMA, and are always negative for S100, distinguishing it from neurofibroma, which is the most common pathological differential diagnosis." (PMID 36092267, 2022). "Immunohistochemical staining was positive for S-100 but negative for c-KIT, CD34, α-SMA, and desmin; these morphological and immunohistochemical characteristics were consistent with the diagnosis of neurofibroma." (PMID 30178113, 2018). "Immunohistochemical staining was positive for S-100 but negative for c-KIT, CD34, α-SMA, and desmin, and these morphologic and immunohistochemical characteristics were consistent with a diagnosis of neurofibroma." (PMID 30178113, 2018). "Besides CD34, neuron-glial antigen 2 (NG2) was also reported as a nerve fibroblast marker but was not further validated in neurofibroma or MPNST." (PMID 34445326, 2021). "Neurofibroma (distinguished by S100 positivity), dermatofibrosarcoma protuberans of myxoid type (prefers trunks and extremities and EMA negative), superficial angiomyxoma (usually head and neck), low‐grade fibromyxoid sarcoma and myxofibrosarcoma (rare on acral surfaces and negative for CD34)." (PMID 36092267, 2022).
myelofibrosis (42 papers, 2012 to 2026). A partial or complete replacement of the bone marrow stroma by fibrous tissue. "Previously, a threshold of 100 CD34-positive cells per μl had been described to be associated with unfavourable prognosis in myelofibrosis patients." (PMID 41540281, 2026). "We therefore assessed the activity of CBL0137 in primary patient samples and murine models of Jak2-mutated MPN and found it preferentially targets CD34+ stem and progenitor cells from myelofibrosis patients by comparison with healthy control cells." (PMID 37253035, 2023). "Single-cell targeted mutation analysis in serial samples from patients with myelofibrosis has revealed the very high level of clonal dominance in the CD34+ compartment seen in almost all patients with myelofibrosis." (PMID 33641869, 2021). "In MPNs, a high number of circulating CD34-positive cells at the time of diagnosis can be used to efficiently distinguish primary myelofibrosis from other MPNs with a threshold of 10 or 15 circulating CD34-positive cells per microliter of peripheral blood." (PMID 41540281, 2026). "We then examined CD34-positive cell quantification during follow-up in patients with primary or secondary myelofibrosis (n = 178 measurements from n = 68 patients)." (PMID 41540281, 2026). "First, we demonstrate that an increase of CD34-positive cell quantification during PV and ET follow-up is highly specific of secondary myelofibrosis." (PMID 41540281, 2026). "In fact, a recent report found a correlation between CD34-positive cells and spleen size response in patients with myelofibrosis who were treated with Ruxolitinib." (PMID 41540281, 2026). "A multicentric prospective study is necessary to confirm our results and determine the impact of circulating CD34-positive cells on the prognosis of myelofibrosis with a standardized monitoring schedule." (PMID 41540281, 2026). "Both absolute values and relative variations of CD34-positive cell count showed good performances for the diagnosis of myelofibrosis evolution with areas under the curves of 0.901 and 0.881, respectively." (PMID 41540281, 2026). "CD34-positive cell count showed an AUC of 0.901 for the diagnosis of post-ET/PV myelofibrosis, with a sensitivity of 54.8%, a specificity of 99.5%, a PPV of 89.5% and a NPV of 96.3% for the threshold of 15 cells/μL." (PMID 41540281, 2026). "Circulating CD34-positive cells at diagnosis can be used to distinguish primary myelofibrosis from other MPNs with a threshold of 10/μL." (PMID 41540281, 2026). "Then, we examined the evolution of CD34-positive cell count in patients with primary or secondary myelofibrosis and found a correlation with treatment response and an association with overall survival, independently of the usual prognostic scoring systems." (PMID 41540281, 2026). "We retrospectively include 180 patients with MPN (90 ET, 55 PV and 35 myelofibrosis) with at least two measurements of circulating CD34-positive cells." (PMID 41540281, 2026). "A few studies demonstrated that in patients with myelofibrosis who received ruxolitinib or navtemadlin (a MDM2 inhibitor) circulating CD34-positive cells decreases progressively during treatment." (PMID 41540281, 2026). "Overall, we demonstrate that an increase in absolute value for circulating CD34-positive cells greater than the threshold of 10/μL in peripheral blood was highly indicative of secondary myelofibrosis in PV/ET patients during follow-up." (PMID 41540281, 2026). "The last dataset includes pre- and post-treatment scRNA-seq data of CD34+ cells from a patient with primary myelofibrosis." (PMID 39226185, 2024). "Organoids were seeded with CD34+ HSPCs from healthy donors (n = 7) and patients with myelofibrosis (n = 10)." (PMID 36351055, 2023). "In line with our data, Andréasson and colleagues described increased levels of CD34+ cells in PB from myelofibrosis patients in comparison to PV and ET." (PMID 36269400, 2022).
myelofibrosis (continued). "In pathological situations, the number of CD34+ and of HSPCs can be either lower, as in Fanconi anemia, unchanged, as in low risk BM failure MDS, or increased, as in high risk MDS and in myelofibrosis." (PMID 32987729, 2020). "An increase in circulating CD34+ cells has been described in myelofibrosis with myeloid metaplasia in adults and in RAEB in adults and in children, associated with a low apoptotic rate." (PMID 23756559, 2013). "Indeed, the test had better specificity with untreated patients, and we also found that some myelofibrosis patients normalized their CD34-positive cells during treatment." (PMID 41540281, 2026). "Finally, we assessed the prognostic significance of circulating CD34-positive cells in patients with primary or secondary myelofibrosis." (PMID 41540281, 2026). "CD34+ cells isolated from peripheral blood of JAK2V617F mutated myelofibrosis patients and non-diseased controls were labelled with CellTraceTM to allow analysis of both cell division and differentiation." (PMID 37253035, 2023). "Internal consistency analysis regarding evaluation of the immunohistochemical markers yielded good or excellent results for myelofibrosis, nestin niches, CD34-positive blast counts, and counting of granzyme B, T-bet, FoxP3, CD3, CD4, CD8, and E-cadherin positive cells." (PMID 33704530, 2021). "To determine the cellular and molecular basis for aberrant megakaryopoiesis in myelofibrosis, we performed single-cell transcriptome profiling of 135,929 CD34+ lineage− hematopoietic stem and progenitor cells (HSPCs), single-cell proteomics, genomics, and functional assays." (PMID 32386542, 2020). "Interestingly, MEG3 overexpression has also been detected in CD34+ cells from patients with primary myelofibrosis (found in 65% of patients), and this upregulation was related to increased blast counts and higher percentages of circulating CD34+ cells." (PMID 30223454, 2018). "Notably, Stathmin 1 mRNA levels were highly expressed in CD34+ cells from primary myelofibrosis patients." (PMID 26356819, 2015). "Thus, reduced CXCR4 expression has been reported on circulating CD34+ cells from patients with myelofibrosis." (PMID 24454890, 2014). "Thus, most recently ROS accumulation in JAK2V617F-positive cells has been shown to be associated with a significant decrease in gene expression of CAT - both in a mouse model and in CD34+ cells from PV and myelofibrosis patients." (PMID 25397683, 2014). "Furthermore, the expression profile of mitotic regulators in CD34 + patient-derived cells allows to faithfully distinguish patients from healthy controls, as well as to differentiate primary and secondary myelofibrosis from essential thrombocythemia and polycythemia vera." (PMID 38308077, 2024). "This validates combinatorial targeting of stem cell (e.g., CD34) and megakaryocyte (e.g., G6B) surface antigens, e.g., with bi-specific antibody therapies as a potential strategy worthy of further investigation for selective ablation of the myelofibrosis clone." (PMID 32386542, 2020). "Then we focused on primary and secondary myelofibrosis (MF) and found that patients achieving partial or complete response (per IWG-MRT criteria) had lower CD34-positive cell levels." (PMID 41540281, 2026). "We and others have previously reported CXCR4 to be significantly downregulated in MPNs, in particular in myelofibrosis, consistent with previous studies displaying downregulation of CXCR4 in CD34+ cells." (PMID 35771847, 2022). "Myelofibrosis is characterized by an expansion of the HSPC pool and by egress of CD34+ positive cells from stem cell niches into the circulation to seed extramedullarily in the spleen and liver." (PMID 25397683, 2014). "In patient 1, whose PV had progressed to myelofibrosis, JAK2V617F burden was around 100% in CD34+ cells and a 20q deletion was detected in a fraction of these cells." (PMID 24066127, 2013).
myelofibrosis (continued). "The median CD34-positive cell count per μl was 19.9 (0.9–636.0) and 1.5 (0.1–36.4) for patients with and without evolution to secondary myelofibrosis, respectively." (PMID 41540281, 2026). "Among patients who transformed into secondary myelofibrosis, 4 were not receiving treatment, 9 received anagrelide, 13 received hydroxyurea and 7 received alpha-pegylated interferon at the time of CD34-positive cell quantification." (PMID 41540281, 2026). "The absence of an increased CD34+ blast population suggested that, although there were signs of disease progression, transformation to advanced myelofibrosis had not yet occurred." (PMID 40422594, 2025). "Ruxolitinib had a similar effect on HSPCs (CD34+CD38−CD45RA−) derived from the peripheral blood of 4 patients with myelofibrosis with high white blood cell counts, none of whom had previously received ruxolitinib or interferon." (PMID 39374575, 2025). "Multi-parameter flow cytometric analysis of the CD34+ lineage (lin)− HSPC compartment in peripheral blood samples from healthy mobilized apheresis donors and patients with myelofibrosis was performed to compare frequencies of the classically defined HSPC subsets." (PMID 32386542, 2020). "Taken together, our data suggest that PMF monocytes induce myelofibrosis-like phenotype in immunodeficient mice and that PMF and normal BM-derived CD14+/CD34- monocytes give rise to megakaryocyte progenitor cells." (PMID 31569199, 2019). "A murine model incorporating a humanised ossicle niche has demonstrated engraftment of myelofibrosis from the CD34+, CD38− HSC population only, with no engraftment in the CD34+, CD38+ progenitor population, suggesting that the initiating cell resides within this HSC population." (PMID 34193229, 2021).
acute leukemia (41 papers, 2011 to 2025). A clonal (malignant) hematopoietic disorder with an acute onset, affecting the bone marrow and the peripheral blood. "Among host risk factors, female sex, history of multiple chemotherapy regimens, and diagnosis of acute leukemia remained independently associated with low circulating CD34+ cell counts in Koreans." (PMID 28666004, 2017). "We also demonstrated that Val-ILs could reduce the risk of contamination of CD34+ hematopoietic stem cells by acute leukemia cells during autologous peripheral blood stem cell transplantation, which is a significant advantage for clinical applications." (PMID 38734740, 2024). "This may explain the result of a meta-analysis comparing BM or PB CD34+ cells for allogenic HSC transplantation in 1521 adults with acute leukemia: transplanted PB CD34+ cells were associated with a higher rate of GvHD." (PMID 35011669, 2021). "CD34 is a marker for hemopoietic progenitors and can be used to assess for a pathology such as an acute leukemia." (PMID 40104156, 2025). "Slides 3 and 4 show positive staining of several blast cells for CD34, suggesting the diagnosis of acute leukemia." (PMID 40142797, 2025). "Our analysis revealed a paradoxical impact of CD34+ stem cell dose on haplo-PBSCT outcomes in acute leukemia." (PMID 40773143, 2025). "A cut-off of >18% CD18+/MCHII−/CD4− cells was used in a proposed algorithm to diagnose AML in dogs with an acute leukemia consisting of >10% or > 1 × 109/L CD34+/MHCII− cells." (PMID 39224452, 2024). "This staining pattern contrasts with the anti-human CD18 antibody, which only stains neutrophils and monocytes in canine blood and was used in a recently proposed scheme for classification of CD34+ acute leukemia." (PMID 39224452, 2024). "In 134 acute leukemia patients, the B7-H3 membrane protein expression was substantially superior in CD34+ cases, with a 44.8% positive rate, and predicted an unfavorable outcome in AML patients." (PMID 34787059, 2021). "Acute leukemias are due to an anomaly of the stem cell characterized among other things by the expression of CD34+ CD38− surface markers." (PMID 23667721, 2013). "We therefore proposed to investigate the prognostic value of the expression of CD34+ CD38− markers in acute leukemias in Abidjan." (PMID 23667721, 2013). "We observed an inverse correlation between levels of c-MYC mRNA and miR-27a, miR-23a, and miR-24 expression in normal CD34+ HSPCs and acute leukemias, suggesting that c-MYC contributes to the regulation of the miR-23a cluster in the hematopoietic system." (PMID 23236401, 2012). "In this study, we determined the expression of miR-27a in CD34+ HSPCs and its expression and effects in human acute leukemias." (PMID 23236401, 2012). "CD34 is the human hematopoietic progenitor antigen and is, expressed in nearly 40% of de novo acute leukemia cases." (PMID 23213544, 2011). "We report a case of acute leukemia CD34+/-HLADR+CD7+CD38+cyCD3- in which a diagnosis of AUL was considered." (PMID 22937302, 2011). "CD34 antigen is expressed by early hematopoietic progenitor cells and acute leukemia cells." (PMID 33773558, 2021). "Because of the increase in sensitivity for relapse detection, in acute leukemia patients, we also perform chimerism analysis in unseparated BM (as well as in BM-isolated CD34+ cells in CD34+ neoplasms) every three months for the first year after HSCT and every six months for the second year." (PMID 32854376, 2020). "Multivariate linear regression analysis revealed that female sex, diagnosis of acute leukemia, history of multiple chemotherapy regimens, and RXFP4 genotype (TT and TA) remained independently associated with lower circulating CD34+ cell count after mobilization in the Korean set." (PMID 28666004, 2017).
acute leukemia (continued). "In contrast to high expression of the miR-23a cluster in CD34+ HSPCs, thought to include the cells of origin of acute leukemias, expression of miR-27a was significantly decreased in 64–66% of acute leukemia cell lines and primary samples examined by qRT-PCR or microarray." (PMID 23236401, 2012). "Flow cytometry of bone marrow biopsy revealed an immature (blast) cell population expressing CD5, CD34, and CD38, highly suggestive of acute leukemia, particularly AML, given the co-expression of CD13 and CD33 found in peripheral blood." (PMID 40978971, 2025). "However, when considering acute leukemias and cancers that originate from transformation of more immature progenitor cells largely preserving the properties of the “original” cell phenotype, it would be expected that this signaling pathway would be also active in CD34‐positive ALL." (PMID 37867416, 2023). "Flow cytometry data indicated that the markers CD34, CD33, CD13, and CD7 were common in SET-CAN/NUP214 positive acute leukemia, including ALL." (PMID 35905214, 2022). "In dogs with acute leukemias, regardless of lineage, tumor cells often express the stem cell marker, CD34, while lacking MHCII, thus the different types are distinguished by expression of lineage-associated antigens." (PMID 39224452, 2024). "The precursor marker CD34 is inconsistently expressed by blast cells; therefore, the absence of expression in our case did not exclude a diagnosis of acute leukemia." (PMID 39289176, 2024). "As a control, we used HL-60 cell line, a BCR-ABL1-negative acute leukemia, since normal healthy CD34+ bone marrow cells are not considered as a well-suited control cells for BP-CML cell lines harboring several genetical abnormalities." (PMID 33003326, 2020). "This prompted initial consideration of acute leukemia, although the immature cell markers CD34, CD10, and TdT were negative." (PMID 26347832, 2015). "We demonstrated that primary acute leukemia cells were sensitive to α-bisabolol at concentrations that did not affect their normal counterpart (i.e. normal CD34+ and CD33+ myeloid cells)." (PMID 23056396, 2012). "For example, Cluster 1 includes the CD34+ oncoprotein-negative control sample as well as 8 AML samples, 2 infant ALLs, 1 mixed phenotype acute leukemia (MPAL), and an AML that resulted from a lineage-switching event that occurred during treatment with the menin inhibitor." (PMID 39472576, 2024).